FSTL1 (follistatin like 1)
Diseases named in the same sentence as FSTL1 in open-access papers (continued):
Sharing a sentence is not in itself a finding about the gene and the disease.
triple-negative breast carcinoma (1 paper, 2021). An invasive breast carcinoma which is negative for expression of estrogen receptor (ER), progesterone receptor (PR), and human epidermal growth factor receptor 2 (HER2). "Our study aims to detect the underlying mechanism of the suppressive effect of Follistatin-like 1 (FSTL1) on lung metastasis of triple negative breast cancer (TNBC)." (PMID 33639614, 2021).
tuberculosis (1 paper, 2024). A chronic, recurrent infection caused by the bacterium Mycobacterium tuberculosis. "Given the central roles of macrophages, inflammatory mediators, and fibrosis in M. tuberculosis infection, understanding how Fstl1 polymorphisms and FSTL1 function in vivo may inform TB pathogenesis, and host-directed therapy." (PMID 38861581, 2024).
Ureteral obstruction (1 paper, 2021). Obstruction of the flow of urine through the ureter. "We also studied the effect of FSTL1 on cultured human kidney cells, and then extended the work to mice with unilateral ureteral obstruction." (PMID 34502419, 2021).
urinary tract obstruction (1 paper, 2021). Blockage of the normal flow of contents of the urinary tract. "Fstl1 and its cognate receptors are therefore up-regulated in two different models of experimental CKD, one associated with early glomerular injury and progressive proteinuria and another associated with urinary tract obstruction." (PMID 34502419, 2021).
tumor (62 papers, 2007 to 2026). "FSTL1-deficient mice exhibited increased susceptibility to lung metastases, characterized by increased oxidative stress, inflammation, and tumor progression." (PMID 41458545, 2025). "High FSTL1 level in FAP positive fibroblasts is associated with poor patient prognosis, and targeting FSTL1 can inhibit tumor malignancy and extend survival in tumor-bearing mice." (PMID 40755769, 2025). "GPNMB and FSTL1 have been linked to tumor invasion, metastasis, and modulation of the extracellular matrix." (PMID 40805206, 2025). "Based on immunohistochemical data from clinical samples, we have observed that high expression of FSTL1 is closely associated with local tumor infiltration." (PMID 38605354, 2024). "We demonstrated that FSTL1 inhibited M2-like tumor-associated macrophage recruitment toward the lungs by suppressing CSF1, VEGF-α, and TGF-β secretion in 4T1 cells." (PMID 37238210, 2023). "The low ratio of FSTL1 mRNA expression between the tumor and its matched adjacent tissue was associated with the poor prognosis in CC." (PMID 36756161, 2023). "Meanwhile, the overexpression of FSTL1 also caused a decrease in MMP2 expression which is related to tumor metastasis." (PMID 36756161, 2023). "In our study, we found that FSTL1 was positively associated with fibroblasts and negatively associated with tumor purity." (PMID 35450397, 2022). "The increased metastatic growth of 4T1 cells in lung inhibited the activity of Th1 and CD8+ T cells in lungs of FSTL1 deficiency mice, and in turn, fewer anti-tumour T lymphocytes accelerated the progression of lung metastasis." (PMID 33639614, 2021). "Flow cytometry also revealed a decreased in the proportions of CD4+ and CD8+ T cells in lungs of Fstl1+/- mice, these findings implied that FSTL1 deficiency reduced the infiltration of anti-tumor T cells in metastatic lung lesions of TNBC." (PMID 33639614, 2021). "Due to the heterogeneity in the different cell lines and cancers and the complexity of the multiple mechanisms underlying tumour development, our knowledge on the role of FSTL1 during cancer development and progression is still fragmented and limited." (PMID 29594389, 2018). "Our data verified that the overexpression of FSTL1 in CRC tissues was associated with the depth of tumour infiltration and the distant metastasis." (PMID 29844309, 2018). "FSTL1 can confer bone polarity on tumor cells by inducing the bone metastasis-associated molecular expression such as CCR2, CXCR4, and RANKL." (PMID 25883937, 2015). "al, whereby FSTL1-deficient mice displayed increased levels of IH-induced tumor metastasis." (PMID 41458545, 2025). "Given the clinical relevance of these findings, we speculated that FSTL1 might be linked to tumor Epithelial-Mesenchymal Transition." (PMID 38605354, 2024). "Critically, FSTL1 is tightly linked to sorafenib resistance, and combining an anti-FSTL1 antibody with sorafenib prolonged mice survival with reduced tumor stemness, illustrating the potential clinical benefits of FSTL1 targeting, either as a single agent or in combination with sorafenib." (PMID 36708970, 2023). "FSTL1 deficiency reduced anti-tumor T cells in lung affected by metastasis." (PMID 33639614, 2021). "In this study, we investigated the expression of FSTL1 in GC using bioinformatics analysis, as well as clinical samples, and analyzed the association of FSTL1 expression with different TILs in TME using the Tumor Immune Estimation Resource (TIMER) database and CIBERSORT method." (PMID 33292276, 2020). "Hence, high FSTL1 expression can cause a substantial increase in immune cell tumor infiltration." (PMID 33292276, 2020). "The rise in pathological markers was attenuated by FSTL1 overexpression, which normalized oxidative stress and inflammatory pathways and reduced tumor cell migration." (PMID 41458545, 2025).
tumor (continued). "miR-198, an exonic miRNA located in the last non-coding exon 11 of the FSTL1 (Follistatin Like 1) gene on chromosome 3q13.33, acts as a tumor suppressor in several cancers." (PMID 39697236, 2024). "The results revealed a significant correlation between high FSTL1 expression and larger tumor size, as well as local tissue infiltration (p < 0.05)." (PMID 38605354, 2024). "Clinical samples analysis revealed a correlation between high FSTL1 expression and adverse parameters such as tumor size and local infiltration in cSCC patients, confirming its role as a pro-oncogenic molecule." (PMID 38605354, 2024). "Here, we demonstrate for the first time that FSTL1 is an oncogene in cSCC, with elevated expression in tissues and cells correlating with poor prognostic features like tumor size and local infiltration." (PMID 38605354, 2024). "In vivo experiments involved injecting sh-FSTL1 or control A431 cells into nude mice, revealing significantly smaller tumor volumes and weights in the sh-FSTL1 groups compared to controls." (PMID 38605354, 2024). "FSTL1 is an extracellular glycoprotein and has previously been reported to play both oncogenic and tumor-suppressive roles in various cancer types." (PMID 39796643, 2024). "And transcriptional data reveal that compared to the adjacent non-tumorous samples, expression of COL3A1, COL1A2, FBN1, IGFBP7, and FSTL1 was significantly elevated in the tumor tissue." (PMID 38478111, 2024). "To determine the molecular basis of the anti-tumor activity of FSTL1 in CC, we first examined the Smad-mediated BMP4 signaling." (PMID 36756161, 2023). "Specifically, NEAT1+ tumor cells with the CSCs phenotype were observed in the initial portion, followed by two separate trajectory branches: apoptotic CSCs FSTL1+ tumor cells and EMT tendency and immune-associated S100A4+ tumor cells." (PMID 37430270, 2023). "The low expression of FSTL1 calculated based on the mRNA expression ratio between the tumor and its matched adjacent tissues can predict the poor prognosis of CC to a certain extent." (PMID 36756161, 2023). "FSTL1, a well-known tumor suppressor in different types of cancer, has recently been reported as a potential regulator of macrophage polarization." (PMID 37238210, 2023). "Recent studies have reported that the tumor suppressor function of FSTL1 can further predict the prognosis of patients." (PMID 36756161, 2023). "This corresponded to a lower level of FSTL1 protein in the tumor than in its matched adjacent tissues." (PMID 36756161, 2023). "Our data demonstrated the tumor suppressor effect of FSTL1, suggesting its potential role as a therapeutic target and a prognostic marker for CC." (PMID 36756161, 2023). "Here, we found that the decreased FSTL1 mRNA expression ratio between the tumor and its matched adjacent tissues, instead of the expression of FSTL1 mRNA itself, is correlated with the FIGO stage." (PMID 36756161, 2023). "Follistatin-like protein 1 (FSTL1), a widely expressed glycoprotein in human and mouse tissues, is a tumor suppressor in various cancers and a regulator of macrophage polarization." (PMID 37238210, 2023). "Here we provided new insights into the pathogenesis of CC and demonstrated the tumor suppressor effect of FSTL1 in CC." (PMID 36756161, 2023). "Consistently, FSTL1 blockade reverses these tumor-initiating phenotypes, sensitizes tumors to sorafenib, and prolongs mice survival." (PMID 36708970, 2023). "FSTL1 drives stemness acquisition and malignant progression in HCC cells, patient-derived organoids, and tumors, and effective tumor control is accomplished by FSTL1 blockade." (PMID 36708970, 2023). "The expression of DIP2A (the receptor of FSTL1) in tumor cells is the key to FSTL1-induced immune resistance." (PMID 35805015, 2022). "The snail+ tumor cells also produce follistatin-like 1 (FSTL1) to promote tumor EMT in an autocrine manner, and indirectly through the induction of immune exhaustion and dysfunction, and apoptosis in CTLs." (PMID 36211375, 2022).
tumor (continued). "Tumor-infiltrating lymphocytes (TILs) and lung microenvironment infiltrated T lymphocytes were stained by IHC in the lung slices of WT and Fstl1+/- mice after orthotropic implantation of 4T1 cells." (PMID 33639614, 2021). "The desmoplastic signature of myofibroblastic CAFs includes 30 secreted proteins, some of them overexpressed specifically in the tumor stroma (e.g., follistatin-related protein 1 (FSTL1))." (PMID 33557173, 2021). "The vast difference of FSTL1 function in vivo and in vitro drew our attention to the tumor microenvironment." (PMID 33639614, 2021). "We found ACAP1, IFIT3 and TAP1 were upregulated in tumor samples, while ADAMTS9, COL6A2, FBN1 and FSTL1 were downregulated in tumor specimens." (PMID 34112144, 2021). "We observed a significant decreased in the percentages of CD4+ and CD8+ T cells in the lungs and peripheral blood of Fstl1+/- tumor free mice." (PMID 33639614, 2021). "Fstl1+/- tumor free mice exhibited significantly reduced proportions of T lymphocyte subpopulations in the periphery blood and lungs, which indirectly reflected the dysfunction of thymus." (PMID 33639614, 2021). "Apparently, the tissue tropism of the tumor cell line is the determining factor in the different, sometimes opposite effect of FSTL1." (PMID 34440203, 2021). "Blocking FSTL1 via a monoclonal antibody suppresses metastasis and disease progression in several mouse tumor models." (PMID 33972406, 2021). "Anti-FSTL1 therapy was more effective in tumor models established by 3LL cells and colon 26 cells with high expression of FSTL1 than in tumor models that barely expressed FSTL1." (PMID 33639614, 2021). "The number of infiltrated CD8+ T cells in primary tumor of Fstl1+/− mice showed a slight decreasing tendency." (PMID 33639614, 2021). "Here, we sought to further clarify the reason for the significant increase in lung metastasis of tumor-bearing Fstl1+/- mice." (PMID 33639614, 2021). "The study effectively revealed useful information about FSTL1 expression, prognostic values, potential functional networks, and impact of tumor immune infiltration in GC." (PMID 33292276, 2020). "Even if the correlation was adjusted based on tumor purity, the majority of tumor-infiltrating immune cell markers were positively correlated with FSTL1 expression in GC." (PMID 33292276, 2020). "The positive expression rate of FSTL1 (43.3%, 104/240) in GC samples was significantly higher than that in adjacent non-tumor tissues (15%, 36/240) (P < 0.001)." (PMID 33292276, 2020). "To further investigate the relationship between FSTL1 and tumor-infiltrating cells, we analyzed the connection between FSTL1 expression and tumor-infiltrating cell markers." (PMID 33292276, 2020). "FSTL1 is involved in multiple tumor biological processes, including metastasis and regulation of the immune response." (PMID 32695142, 2020). "The correlations between FSTL1 and cancer immune infiltrates were analyzed by Tumor Immune Estimation Resource (TIME), Gene Expression Profiling Interactive Analysis (GEPIA), and LinkedOmics database." (PMID 33292276, 2020). "The staining of FSTL1 protein ranged from weak to strong, and the result showed that FSTL1 positive staining was increased in GC tissues than adjacent non-tumor tissues." (PMID 33292276, 2020). "Bioinformatics analysis results suggested that FSTL1 mainly involved in tumor progression and tumor immunity." (PMID 33292276, 2020). "Another important aspect of this research is the close connection between FSTL1 expression and tumor-infiltrating immune cells in GC." (PMID 33292276, 2020). "The result showed that expression level of FSTL1 was correlated with tumor size (P < 0.001), lymph node metastasis (P < 0.001), and tumor-node-metastasis (TNM) stage (P = 0.001)." (PMID 33292276, 2020).
tumor (continued). "It is noteworthy that FSTL1 is significantly related to tumor metastasis, and up or down regulation of FSTL1 in different cancers greatly induces their migratory and invasive capacity, leading to tumor dissemination." (PMID 32695142, 2020). "FSTL1-induced immune dysfunction leads to tumor bone metastases and activation of immune evasion mechanisms in patients with non-small cell lung cancer (NSCLC) through the FSTL1-DIP2A axis." (PMID 33292276, 2020). "The expressions of three tumor-associated proteins, TGF-β, CTSB and FSTL1, were examined using immunohistochemical staining and Western blotting." (PMID 32050622, 2020). "KEGG pathway analysis found enrichment in pathway in cancer, focal adhesion, PI3K-Akt signaling pathway, and ECM-receptor interaction, which indicated that elevation of FSTL1 was significantly correlated with tumor development and immune response." (PMID 33292276, 2020). "Mice bearing Fstl1-overexpressing D54 cells showed increased tumor growth, compared with mice implanted with vector control-infected cells." (PMID 30542120, 2019). "In colon cancer, Fstl1 level is greatly increased in the tumor stroma, making it a candidate biomarker for cancer stroma." (PMID 30542120, 2019). "The results of studies using array-based comparative genomic hybridization to analyze human genome sequences have suggested that Fstl1 is a candidate tumor-suppressor gene or oncogene." (PMID 30542120, 2019). "FSTL1 plays a tumor suppression role possibly via repressing the NF-κB and HIF-2α signaling pathways." (PMID 29357946, 2018). "Xenograft tumours in spleen and metastatic nodules in liver were earlier detected in the group of FSTL1 overexpression (FSTL1) compared with those in the control group (Vector)." (PMID 29844309, 2018). "IHC staining confirmed that the tumours derived from FSTL1 group exhibited higher FSTL1 expression levels than tumours derived from control cells." (PMID 29844309, 2018). "In HCC, high levels of FSTL1 correlate with larger tumours, advanced tumour/node/metastasis (TNM) stages, metastasis, and poor post-surgical outcomes (hazard ratio = 1.84; p = 0.015)." (PMID 29594389, 2018). "In vitro transfection of fibroblasts (mouse NIH3T3 and rat 208F) using oncogenes like ras, myc, or fos induces a tumourigenic phenotype and downregulation of Fstl1 expression, suggesting a tumour suppressor role." (PMID 29594389, 2018). "A similar effect is also observed during cancer progression, in which FSTL1 plays an important role in immune dysfunction regulating thymocyte maturation: in vivo inhibition of Fstl1 increases the tumour-specific CD8+ T-cell response." (PMID 29594389, 2018). "FSTL1 is regarded as a tumour suppressor for inducing apoptosis of cancer cells in ovarian and endometrial cancers." (PMID 29844309, 2018). "In view of the special role of FSTL1 in inflammation, the effect of FSTL1 in tumour progression has attracted the interest of researchers." (PMID 29844309, 2018). "Follistatin-like protein 1 (FSTL1) has been reported to have both tumour-promoting and tumour-suppressive characters." (PMID 29844309, 2018). "The reduced levels of expression of Fstl1 in the NPC tumours are reflected in decreased FSTL1 serum levels." (PMID 29594389, 2018). "In the present study, we presented a series of data to identify that FSTL1 functioned as a novel tumor suppressor in ccRCC." (PMID 29357946, 2018). "The switch between expression of the FSTL1 protein and miR-198 is an important regulator of tumour metastasis and wound healing." (PMID 29594389, 2018). "We found that collagen, biglycan, fibulin 2, and FSTL1 can induce tumor cell invasion under the bead, though only collagen seemed to allow cells to migrate through the bead." (PMID 29615735, 2018). "The data indicated that overexpression of FSTL1 was closely related to depth of tumour invasion (P = 0.009), and lymph node metastasis (P = 0.028)." (PMID 29844309, 2018).